GPR63 (G protein-coupled receptor 63)
Description:
Orphan receptor. May play a role in brain function.
Synonyms: PSP24B; PSP24(beta)
Tractability: Small molecule: it belongs to a druggable protein family. Antibody: its Gene Ontology location is reachable by antibodies, with high confidence; UniProt places it where antibodies can reach, with medium confidence; UniProt predicts a signal peptide or a membrane-spanning region; the Human Protein Atlas places it where antibodies can reach.
Target class: Family A G protein-coupled receptor; Membrane receptor
Gene: Protein-coding gene on chromosome 6 (96,794,125 to 96,838,150, reverse strand). Ensembl gene ENSG00000112218.
Subcellular location: Cell membrane
Subcellular location (Human Protein Atlas): Cytosol; Nucleoplasm; Plasma membrane
Gene Ontology:
Molecular function: G protein-coupled receptor activity
Biological process: G protein-coupled receptor signaling pathway
Cellular component: receptor complex; membrane; plasma membrane
Genetic constraint (gnomAD): Loss-of-function variants: 12 observed, 24.32 expected, observed/expected ratio (o/e) 0.49, 90% interval 0.31 to 0.8. The upper end of that interval is the gene's LOEUF score, 0.8, which puts it in group 3 of 6, group 1 being the genes least tolerant of losing a copy. Missense variants: 472 observed, 544.2 expected, observed/expected ratio (o/e) 0.87, 90% interval 0.8 to 0.94. Synonymous variants: 172 observed, 202.43 expected, observed/expected ratio (o/e) 0.85, 90% interval 0.75 to 0.96.
Homologues: Orthologues: chimpanzee GPR63 (99% identical), macaque GPR63 (99% identical), rabbit GPR63 (96% identical), pig GPR63 (95% identical), dog GPR63 (95% identical), guinea pig GPR63 (94% identical), mouse Gpr63 (92% identical), rat Gpr63 (92% identical), tropical clawed frog gpr63 (76% identical), zebrafish gpr63 (66% identical). Paralogues in human: GPR45 (47% identical), GPR78 (17% identical), GPR26 (16% identical).
Diseases named in the same sentence as GPR63 in open-access papers:
GPR63 is named in the same sentence as 8 diseases in open-access papers, as found by Europe PMC text mining. Sharing a sentence is not in itself a finding about the gene and the disease. The quoted sentences say what the papers report.
Tourette syndrome (2 papers, 2015 to 2020). A neurologic disorder caused by defective metabolism of the neurotransmitters in the brain. "A deletion on human chromosome 6 that affects GPR63, NOUFA4, and KLHL32 has been associated with Tourette’s syndrome and obsessive–compulsive disorder." (PMID 31840818, 2020). "Genome-wide association studies revealed a risk loci for bipolar disorder downstream of POU3F2, and a region around KLHL32, GPR63 and NDUFA4 associated with Tourette syndrome and obsessive-compulsive disorder, indicating the importance of these enriched regions for establishing cortical functions." (PMID 26076492, 2015).
ciliopathies (1 paper, 2019). "Although loss of Gpr63 alone does not seem to cause a significant phenotype, this work suggests Gpr63 may be a risk factor underlying some of the variability seen in the ciliopathies." (PMID 31730647, 2019).
spina bifida aperta (1 paper, 2019). "These alleles affect ciliary localization of GPR63 in vitro and genetically interact with Ttc21baln/aln as Gpr63;Ttc21b double mutants show unique phenotypes including spina bifida aperta and earlier embryonic lethality." (PMID 31730647, 2019).
GPR63 also shares sentences with these, for which no sentence is quoted: Anxiety (1 paper); bipolar disorder (1); microcephaly (1); obsessive-compulsive disorder (1); spina bifida (1).